ANGPTL8 (angiopoietin like 8)
Description:
Hormone that acts as a blood lipid regulator by regulating serum triglyceride levels. May be involved in the metabolic transition between fasting and refeeding: required to direct fatty acids to adipose tissue for storage in the fed state (By similarity).
Synonyms: C19orf80; RIFL; TD26; PRO1185; PVPA599
Tractability: Antibody: UniProt places it where antibodies can reach, with high confidence; its Gene Ontology location is reachable by antibodies, with high confidence; UniProt predicts a signal peptide or a membrane-spanning region.
Target class: Secreted protein
Gene: Protein-coding gene on chromosome 19 (11,237,502 to 11,241,943, forward strand). Ensembl gene ENSG00000130173.
Subcellular location: Secreted
Subcellular location (Human Protein Atlas): Golgi apparatus; Nucleoplasm; Predicted to be secreted
Pathways (Reactome):
Transport of small molecules: Assembly of active LPL and LIPC lipase complexes
Gene Ontology:
Molecular function: protein binding
Biological process: positive regulation of protein processing; regulation of lipid metabolic process; regulation of lipoprotein metabolic process; triglyceride homeostasis; type B pancreatic cell proliferation; lipid metabolic process
Cellular component: extracellular region
Genetic constraint (gnomAD): Loss-of-function variants: 24 observed, 18.98 expected, observed/expected ratio (o/e) 1.26, 90% interval 0.91 to 1.75. The upper end of that interval is the gene's LOEUF score, 1.75, which puts it in group 6 of 6, group 1 being the genes least tolerant of losing a copy. Missense variants: 230 observed, 228.29 expected, observed/expected ratio (o/e) 1.01, 90% interval 0.9 to 1.12. Synonymous variants: 88 observed, 92.94 expected, observed/expected ratio (o/e) 0.95, 90% interval 0.8 to 1.13.
Homologues: Orthologues: chimpanzee ANGPTL8 (99% identical), macaque ANGPTL8 (92% identical), dog ANGPTL8 (77% identical), mouse Angptl8 (73% identical), pig ANGPTL8 (72% identical), guinea pig ANGPTL8 (58% identical), rat Angptl8 (57% identical).
Diseases named in the same sentence as ANGPTL8 in open-access papers:
ANGPTL8 is named in the same sentence as 118 diseases in open-access papers, as found by Europe PMC text mining. Sharing a sentence is not in itself a finding about the gene and the disease. The quoted sentences say what the papers report.
Insulin resistance (60 papers, 2015 to 2025). Increased resistance towards insulin, that is, diminished effectiveness of insulin in reducing blood glucose levels. "Hepatokines such as fetuin-A promote renal insulin resistance and inflammation, while proteins like angiopoietin-like protein 8 (ANGPTL8) and selenoprotein p are implicated in lipid imbalance and oxidative stress, exacerbating nephron damage." (PMID 41007724, 2025). "The increase in ANGPTL8 synthesis was ascribed to albumin loss, a condition that leads to insulin resistance and heightened insulin requirements in individuals with T2D and albuminuria." (PMID 38790911, 2024). "ANGPTL8’s role in lipid regulation suggests that a continuous rise in its levels can cause dyslipidemia and heightened insulin resistance, exacerbating metabolic stress and contributing to the onset of metabolic disorders such as T2D and DN." (PMID 38790911, 2024). "The rise in ANGPTL8 production was attributed to losing albumin, which causes insulin resistance and increased need for insulin in people with T2D and albuminuria." (PMID 37762544, 2023). "Recent studies have demonstrated that this variation in ANGPTL8 in metabolic syndrome is associated with a lower risk of hypercholesterolemia, hyperglycemia, insulin resistance, etc.." (PMID 37679750, 2023). "ND-fed ERRα3SA mice also showed dysregulated genes encoding proteins involved in hepatic lipid metabolism such as Acot11 and Angptl8, which have been shown to be closely associated with insulin resistance and NAFLD34,35." (PMID 35440636, 2022). "Multivariate analyses were performed in order to detect the association between plasma ANGPTL8 with variables related to insulin resistance (Model I) and liver function and fat percentage (Model II)." (PMID 34884755, 2021). "They reported that the level of ANGPTL8 negatively correlated with hyperglycaemia and insulin resistance, the conditions which are normally associated with metabolic syndrome, but not with overweight or obesity." (PMID 32537470, 2020). "The association of ANGPTL8 with insulin resistance, blood glucose, C-peptide and glycosylated haemoglobin (HbA1C) have not offered clear results." (PMID 32069954, 2020). "ANGPTL8 has been reported to be a regulator of lipid metabolism, and it is associated with insulin resistance (IR) and metabolic syndrome (MetS)." (PMID 31346314, 2019). "On the other hand, ANGPTL8 has been linked to insulin resistance and lipoprotein metabolism, two functionally important processes in the development of type 2 diabetes and CVD." (PMID 29973202, 2018). "ANGPTL8 level was associated with blood glucose, insulin, and insulin resistance as measured by homeostatic model assessment-insulin resistance (HOMA-IR) in the nondiabetic subjects only." (PMID 27672665, 2016). "ANGPTL8 was proposed to underlie the β-cell mitogenic signals that resulted in β-cell expansion in response to insulin resistance." (PMID 27410263, 2016). "ANGPTL8 has emerged as a central regulator of glucose and lipid metabolism, and its dysregulation has been associated with various cardio-metabolic disorders, including obesity, insulin resistance and dyslipidaemia." (PMID 40276549, 2025). "Notably, the association of ANGPTL8 with insulin resistance provides insight into its potential underlying mediating role in steatosis/steatohepatitis." (PMID 40276549, 2025). "Additionally, there is mounting evidence of a positive association between circulating ANGPTL8 levels, insulin resistance, and T2DM." (PMID 37679750, 2023). "The present study found that the circulating ANGPTL8 levels contribute to elevated TG levels and may also be associated with obesity and insulin resistance in patients with diabetes." (PMID 34293055, 2021). "Among the ANGPTLs, ANGPTL8 was particularly important in determining the plasma TG levels; furthermore, ANGPTL8 may be associated with obesity and insulin resistance, as well as lipid metabolism." (PMID 34293055, 2021).
Insulin resistance (continued). "In addition to its relationship with glucose metabolism, ANGPTL8 has also been implicated in both lipid metabolism and insulin resistance, all of which are thought to be involved in the pathogenesis of atherosclerosis." (PMID 30007407, 2018). "Based on its involvement in two key pathways (lipid metabolism and insulin resistance), we hypothesized that the increased ANGPTL8 level caused by insulin resistance in MetS subjects will lead to an increased release of TG into plasma." (PMID 26850725, 2016). "This suggests that interventions that reduce circulating ANGPTL8 levels can improve lipid profiles in diabetes patients with poor TG control and may also lead to improved glucose metabolism through weight loss and improved insulin resistance." (PMID 34293055, 2021). "Functionally, ANGPTL8 worsened insulin resistance and glucose intolerance in obese mice, effects that were reversed by its deletion and recapitulated by CCL5 administration." (PMID 41289013, 2025). "Although ANGPTL8 levels showed some inter-individual variability, this is expected given known influences such as BMI, metabolic status, and insulin resistance." (PMID 40725697, 2025). "Clinical observations in diabetes further show that high circulating ANGPTL8 associates with higher triglyceride levels and insulin resistance, and that concurrent high ANGPTL3 and ANGPTL8 identifies elevated TG and LDL." (PMID 41226996, 2025). "Fasting blood glucose (FBG), high-density lipoprotein cholesterol (HDL-C), triglycerides (TG), ANGPTL8, adiponectin, and insulin resistance (IR) were statistically significant differences observed between the two groups." (PMID 37767256, 2023). "ANGPTL-8 seems to play a supporting role in stimulating proliferation and increasing the pancreatic β-cell mass as well as improving glucose tolerance in insulin resistance, presumably by increasing insulin secretion." (PMID 35457182, 2022). "In high-fat diet-induced gestational diabetes mellitus mice, increased ANGPTL8 was accompanied by decreased phosphorylation of IRβ(Tyr1361) and Akt, and silencing ANGPTL8 ameliorated insulin resistance by inhibiting JNK signaling." (PMID 35851270, 2022). "Moreover, more detailed data analysis showed that ANGPTL8 was significantly correlated with insulin resistance, fasting blood glucose, postprandial blood glucose and glycosylated haemoglobin (HbA1c), which theoretically supported the association between ANGPTL8 and T2DM." (PMID 34582711, 2021). "The tissue distribution of ANGPTL8 was mainly detected in hepatocytes, and the immunostaining was markedly increased in liver sections obtained from patients with insulin resistance and NAFLD." (PMID 34884755, 2021). "Studies in obese children or adolescents, obese adults, women with polycystic ovary syndrome (PCOS) and type 2 diabetes mellitus (T2DM), support our results, since ANGPTL8 were strongly and negatively correlated with all markers of insulin resistance." (PMID 32069954, 2020). "The MetS, as well as dyslipidemia, insulin resistance, and fatty liver disease, is characterized by an increased expression of angiopoietin-like 8 (ANGPTL8; betatrophin)." (PMID 32537470, 2020). "Angiopoietin-like protein 8 (ANGPTL8), an important regulator of lipid metabolism, is increased in diabetes and is associated with insulin resistance." (PMID 32746907, 2020). "Some researchers suggested that the serum ANGPTL8 level was significantly increased in type 2 diabetes patients; the ANGPTL8 level was positively correlated with insulin resistance and negatively correlated with insulin sensitivity." (PMID 31346314, 2019). "ANGPTL8 is a liver-produced protein that has been found to be related to lipid metabolism, MetS, and insulin resistance (IR)." (PMID 31346314, 2019). "PCOS patients with higher insulin resistance had substantially higher circulating ANGPTL8 concentrations." (PMID 31346314, 2019).
Insulin resistance (continued). "Other research suggested that ANGPTL8 levels were increased in women with PCOS and were associated with insulin resistance, hs-CRP, and free testosterone in these patients." (PMID 31346314, 2019). "ANGPTL8 is a predominantly liver expressed gene in humans which has been found up-regulated in insulin resistance, obesity and DM type II." (PMID 30627105, 2018). "The selection of the gene expression data is based on the facts that ANGPTL8 is a predominantly liver expressed gene in humans besides being up-regulated in insulin resistance, obesity and DM type II." (PMID 30627105, 2018). "Circulating level of ANGPTL8 was significantly higher in subject with MetS (metabolic syndrome) as well as subjects with increasing number of MetS components such as insulin resistance and central obesity." (PMID 29973202, 2018). "Aside from TG, ANGPTL8 had also been shown to be connected with blood glucose and insulin resistance." (PMID 30007407, 2018). "Findings of this study have implications in functional characterization of ANGPTL8 with emphasis on the identified genes and pathways and their possible involvement in the pathogenesis of Diabetes Mellitus and Insulin Resistance." (PMID 30627105, 2018). "The relationships between glucose metabolism, insulin resistance and ANGPTL8 have been investigated in previous studies." (PMID 30072957, 2018). "They reported that ANGPTL8−/− mice with insulin resistance induced by a high-fat diet or insulin receptor antagonist S961 had normal beta cell expansion." (PMID 28702052, 2017). "We and others have recently showed that ANGPTL8 level was increased in T2D and its level associated with FBG and insulin resistance in a large human cohort." (PMID 26850725, 2016). "In their paper, Yi and his coworkers showed that S961 induced insulin resistance and was able to upregulate the expression of ANGPTL8 gene in the liver and adipose tissue." (PMID 27672665, 2016). "In this study we showed that ANGPTL8 circulation level was higher in subject with MetS as well as subjects with increasing number of MetS components such as insulin resistance and central obesity." (PMID 26850725, 2016). "We examined ANGPTL8 expression in human and murine fasting-refeeding models and manipulated ANGPTL8 expression specifically in hepatocytes to assess its role in metabolic inflammation and insulin resistance in obese mice." (PMID 41289013, 2025). "Elevated ANGPTL8 levels in steatosis/steatohepatitis have been hypothesized to represent a compensatory mechanism to mitigate hepatic insulin resistance and hyperglycemia, potentially via enhanced β-cell proliferation and insulin secretion." (PMID 40276549, 2025). "In a previous study, we reported a significant rise in the levels of circulating ANGPTL8 in people with T2D compared to those without T2D, which was strongly associated with insulin resistance." (PMID 37762544, 2023). "Due to the well-known function of ANGPTL8 in lipid regulation, it is assumed that its persistent increase results in dyslipidaemia and increased insulin resistance, which aggravates metabolic stress and ultimately leads to the development of metabolic diseases like T2D and complications such as DN." (PMID 37762544, 2023). "Alternatively, some also hypothesized that the rise in serum ANGPTL-8 level in metabolic illnesses might be a compensatory response to the increased insulin resistance." (PMID 37590020, 2023). "ANGPTL8 may drive the progression of diabetic nephropathy through pathways and mechanisms related to insulin resistance or through inflammatory mechanisms." (PMID 36143124, 2022). "Additionally, the cord blood serum ANGPTL8 level was positively correlated with insulin and the homeostatic model assessment for insulin resistance." (PMID 35529083, 2022). "Furthermore, serum ANGPTL8 was higher in individuals with insulin resistance than in those with insulin sensitivity." (PMID 35851270, 2022).
Insulin resistance (continued). "ANGPTL8 is a liver-derived hormone that has been suggested may be capable of regulate insulin resistance." (PMID 34603198, 2021). "In contrast, we revealed that ANGPTL8 levels have a significantly positive correlation with BMI and HOMA2-IR values, which suggests that it may be associated with obesity and insulin resistance in patients with diabetes." (PMID 34293055, 2021). "If this holds true, a dysmetabolic progression occurring during adulthood could disentangle ANGPTL8 function as an adipokine, which could then act to signal comorbidities relating to insulin resistance and NAFLD." (PMID 33067796, 2021). "Besides, the increased expression of ANGPTL8 in insulin resistance model or T2DM suggests that insulin signalling also plays a regulatory role in ANGPTL8." (PMID 34582711, 2021). "Nevertheless, it is interesting to note that a previous study found strong positive associations between ANGPTL8 and metabolic markers in individuals without insulin resistance but not in patients with T2DM." (PMID 33067796, 2021). "Studies have shown that ANGPTL8/betatrophin may regulate PI3K/Akt signaling pathway to alleviate insulin resistance." (PMID 34646087, 2021). "The authors demonstrated that circulating ANGPTL8 levels were positively associated with triglycerides (TG), whereas ANGPTL3 levels were associated with fasting insulin and the homeostasis model assessment of insulin resistance (HOMA-IR)." (PMID 32286392, 2020). "ANGPTL8 is a novel secretory protein that is composed of 198 amino acids, is mainly secreted by liver and adipose tissue, and is closely related to glucose and lipid metabolism and insulin resistance." (PMID 33343659, 2020). "ANGPTL8 has been associated with two functionally important processes in the development of T2DM, insulin resistance and lipid metabolism, and has been also reported to regulate the replication of β-cells in response to insulin resistance." (PMID 29973202, 2018). "Therefore, further studies are required to investigate the interdependence of ANGPTL8 signaling pathway and focal adhesion signaling pathway in regulating glucose homeostasis especially in pathological conditions like insulin resistance and DM." (PMID 30627105, 2018). "Notably, the significant relationship between blood glucose, insulin resistance and ANGPTL8 was mostly found in newly diagnosed type 2 diabetes, whereas the nonsignificant relationship was mostly found in treated type 2 diabetes." (PMID 30007407, 2018). "Because HbA1c, fasting plasma glucose and HOMA-IR were not correlated with ANGPTL8 significantly, the mediator role of insulin resistance and hyperglycemia in the association between ANGPTL8 and ACR were not further evaluated." (PMID 30072957, 2018). "This upregulation of ANGPTL8 expression by insulin resistance was hypothesized to be a mechanism to increase insulin production through increasing β-cell proliferation." (PMID 27672665, 2016). "Indeed, it has been reported that in early NAFLD stages, circulating ANGPTL8 levels may be elevated, potentially serving as a compensatory response to mitigate hepatic insulin resistance and lipid dysregulation." (PMID 40276549, 2025). "Importantly, ANGPTL8 is linked to NAFLD, insulin resistance, and type 2 diabetes." (PMID 40725697, 2025). "Moreover, recent review articles reported that insulin does not alter ANGPTL8 levels in the circulation and that the association of ANGPTL8 with insulin resistance and HbA1c in non-diabetic subjects seems contentious." (PMID 35736472, 2022). "Considering these facts (unknown factors, hyperglycaemia, high intensity of insulin resistance, vitamin D deficiency, etc.), it is impossible to come to any proper conclusion why the level of ANGPTL8 did not increase." (PMID 32537470, 2020). "Therefore, it is speculated that antidiabetic medication might, at least in part, lead to this obscure relationship between insulin resistance, glucose metabolism and ANGPTL8 in type 2 diabetes." (PMID 30072957, 2018).